PGR (progesterone receptor)
Diseases named in the same sentence as PGR in open-access papers (continued):
Sharing a sentence is not in itself a finding about the gene and the disease.
breast cancer (continued). "Triple negative breast cancer is a collection of heterogeneous breast cancers that are immunohistochemically negative for estrogen receptor, progesterone receptor, and ErbB2 (due to deletion or lack of amplification)." (PMID 32349331, 2020). "In advanced breast cancers, AR does not seem to predict the efficacy of first-line antiestrogen endocrine therapy, whereas progesterone receptor and Ki67 were shown to be more potent predictors." (PMID 31952272, 2020). "HER2 positivity is associated with phenotypic and biologic aggression, characterized by an increase in cellular proliferation, motility, invasiveness, metastasis, angiogenesis, decreased apoptosis, and chemotherapy resistance as compared to luminal A (ER+/PgR+, HER2-) breast cancer." (PMID 35582612, 2020). "Based on molecular characterization of estrogen receptor (ER), progesterone receptor (PR), ki-67, and HER-2, Breast cancer can be divided into different types including Lumina A, Lumina B, HER-2 overexpression, basal-like tumours, and ‘normal-like’ breast tumours." (PMID 32248842, 2020). "The lack of progesterone receptor expression in breast cancer has been in recent years repeatedly reported as the factor for poor treatment outcome, which is consistent with our results." (PMID 32235849, 2020). "Specifically, triple-negative breast cancer (TNBC) refers to certain breast cancer lack of expression of progesterone receptor, estrogen receptor, and HER22." (PMID 32908121, 2020). "The breast cancer cell lines MCF7 and T47D are very sensitive to a selection of antihormonal drugs, which prompted us to investigate whether ESR1, PGR, and GREB1 protein show similar abundance profiles across the NCI60 panel as their p-sites." (PMID 32686665, 2020). "Triple-negative breast cancers (TNBC) constitute around 15% of all cases of breast cancer and do not express estrogen receptor (ER), progesterone receptor (PR), and do not overexpress human epidermal growth factor receptor 2 (HER2)." (PMID 33282730, 2020). "Based on the expression status of the estrogen receptor (ER), progesterone receptor (PR) and human epidermal growth factor receptor 2 (HER2), breast cancers are classified as four subtypes including Luminal A, Luminal B, HER2 and triple-negative breast cancer (TNBC)." (PMID 32962246, 2020). "Triple-negative breast cancer (TNBC), accounting for 15–20% of all breast cancers (BC), is defined by the absence of oestrogen receptor (ER), progesterone receptor (PgR), and human epidermal growth factor receptor 2 (HER2) expression on cancer cells." (PMID 32947953, 2020). "On the grounds of the expression of estrogen receptor (ER), progesterone receptor (PR), and human epidermal growth factor receptor 2 (HER2), breast carcinoma is roughly classified into four different molecular subtypes, containing luminal, HER2-enriched, basal-like, and normal-like type." (PMID 32850442, 2020). "Most studies have reported higher percentage of estrogen receptor (ER)-positive/progesterone receptor (PR)-positive tumors among SDBC leading to a higher prevalence of luminal A and a lower prevalence of triple negative (TN) breast carcinomas in this group of tumors." (PMID 32549380, 2020). "Hormone receptor studies such ER, PgR, and HER2/neu are routinely done in breast carcinoma." (PMID 33112549, 2020). "The basal-like molecular subtype can be approximated to the core-basal breast cancer, which is only defined by the absence of ER, PgR, HER2, and the presence of EGFR and cytokeratin 5/6." (PMID 31295913, 2019). "According to the 2017 St Gallen surrogate definitions of the intrinsic subtypes, Ki67, progesterone receptor (PR) and Nottingham histological grade (NHG) are used for prognostic classification of estrogen receptor (ER) positive/HER2-negative breast cancer into luminal A- or luminal B-like." (PMID 30796653, 2019).
breast cancer (continued). "Triple-negative breast cancer (TNBC) is a clinically aggressive subtype of breast cancer that does not express estrogen receptor (ER), progesterone receptor (PR) or human epidermal growth factor receptor 2 (HER2)." (PMID 31315653, 2019). "Frequencies of breast cancers with NLR-low were marginally higher in patients with progesterone receptor-negative, recurrence, and no prior trastuzumab (p = 0.05)." (PMID 30755651, 2019). "Immunohistochemical analysis was performed to evaluate the expression of COX-2, IDO, estrogen receptor (ER), progesterone receptor (PR) and human epidermal growth factor receptor 2 (HER2) on formalin-fixed paraffin-embedded breast cancer tissues of 100 patients." (PMID 31759380, 2019). "A 35-year-old woman with a BRCA2 mutation developed IDC that was ER-, progesterone receptor (PgR)-negative, and HER2-negative, as a primary breast cancer during surveillance, 2 years after receiving her genetic testing results." (PMID 30980249, 2019). "Breast cancers lacking estrogen receptor, progesterone receptor, and HER2 amplification are defined as triple negative breast cancers (TNBC) and account for 15%−20% of breast cancer diagnoses." (PMID 30847405, 2019). "The following molecular subtypes exist for breast cancer: Luminal A (ER+, HER2−, Ki67low, PgRhigh), Luminal B (ER+, HER2−, either Ki67high or PgRlow or ER+, HER2+, any Ki67, any PgR), Her2+ (HER2+, ER−, and PgR−), and triple negative cases (TNBC, HER2−, ER−, PgR−)." (PMID 31461945, 2019). "Positive staining for CAM6/CAM5/E-cad and E-cad/ZEB1 was detected in Her2+ER−PR− (Her2-positive, estrogen receptor–negative, and progesterone receptor-negative) breast cancers more frequently than in other tumors." (PMID 31331982, 2019). "Triple-Negative Breast Cancer (TNBC) is a subtype of breast cancer that lacks expression of the estrogen and progesterone receptor and does not overex-press human epidermal growth factor 2 receptor protein." (PMID 31908742, 2019). "Breast cancer brain metastases (BM) affect younger women disproportionally, including those lacking estrogen receptor (ER), progesterone receptor, and HER2 (known as triple-negative breast cancer; TNBC)." (PMID 30796353, 2019). "As zearalenone and apigenin activated ERs, we tested the potential effect of these molecules on the expression of endogenous E2-dependent genes, such as the chemokine CXCL12, the progesterone receptor (PgR), amphiregulin (AREG) and growth regulation in breast cancer 1 (GREB1)." (PMID 30678243, 2019). "Serum miR-4480 and PgR negative are useful biomarkers for predicting BM in patients with breast cancer." (PMID 31603918, 2019). "DUSP6 is also upregulated in the cytoplasm of primary malignant breast cancer cells in HER2-positive breast cancer patients regardless of estrogen receptor/progesterone receptor (ER/PR) status." (PMID 31238530, 2019). "Triple negative breast cancer (TNBC), a collective term for invasive breast cancers that lack expression of estrogen receptor, progesterone receptor and HER2, is responsible for 15–20% of breast cancers and it accounts for a disproportionate number of breast cancer deaths." (PMID 30846710, 2019). "Triple-negative breast cancer (TNBC), which accounts for about 15% of breast cancer cases, is defined as estrogen receptor (ER)-negative, progesterone receptor (PgR)-negative, and human epidermal receptor 2 (HER2)-negative disease." (PMID 29971631, 2019). "Results from human breast cancer tissues indicated that abnormal expression of PGC-1β was closely related to the clinicopathological characteristics of patients, such as Lymph node metastasis (P = 0.026) and Progesterone receptor (P = 0.026)." (PMID 31007610, 2019). "Triple‐negative breast cancers are ER‐negative, progesterone receptor (PR)–negative, and human epidermal growth factor receptor 2 (HER2)–negative." (PMID 30720861, 2019).
breast cancer (continued). "The presence of these clinical–pathological variables allows a more complete and accurate association between the expression of specific biomarkers (ER, Progesterone Receptor, Human Epidermal Growth Factor Receptor 2-HER2-, molecular subtypes) and ILs with breast cancer bone metastasis incidence." (PMID 31847214, 2019). "TNBC is resistant to common breast cancer therapies, as it lacks the expression of the most common breast cancer targets, namely estrogen receptor (ER), human epidermal growth factor receptor-2 (HER2), and progesterone receptor (PR)." (PMID 31349612, 2019). "The results indicated that ESR1, PGR, EGFR, PTGS2, and Src may be the potential therapeutic target of RYNXC for the treatment of breast cancer." (PMID 30906412, 2019). "Breast cancers that do not express these receptors (as well as the Progesterone receptor (PR)) are termed “triple negative breast cancers” (TNBCs) and have the poorest clinical outcome, reflecting, in part, the fact that they lack targeted therapies." (PMID 30935371, 2019). "Triple negative breast cancer (TNBC), a breast cancer (BC) subtype that lacks estrogen and progesterone receptor expression and has no epidermal growth factor receptor 2 amplification, accounts for about 20% of all breast cancers." (PMID 31572059, 2019). "Parental cell lines were chosen to represent different molecular subtypes of breast cancer and included MCF-7 and ZR-751 cell lines (ER+, PgR+, HER2-), which are hormone-dependent, and the MDA-MB-231 cell line, which is triple negative (ER-, PgR-, HER2-) and consequently hormone-independent." (PMID 30987655, 2019). "According to the status of biomarkers including estrogen receptor (ER), progesterone receptor (PR) and epidermal growth factor receptor 2 (HER2), patients with breast cancer were classified into groups of luminal A, luminal B, HER-2 positive and triple negative." (PMID 31516390, 2019). "Systemic chemotherapy reduces the risk of recurrence and mortality in estrogen receptor (ER) and/or progesterone receptor (PR)-positive breast cancer patients irrespective of lymph node status." (PMID 31619259, 2019). "The expression levels of E-cadherin, vimentin, DDR1, DDR2, α2 integrin, α11 integrin, COL1A1, MT1-MMP, BIK, estrogen receptor α, progesterone receptor, and HER2 mRNAs in 58 breast cancer cell lines were analyzed in silico, by using the Broad-Novartis Cancer Cell Line Encyclopedia (CCLE) database." (PMID 31130862, 2019). "Triple-negative breast cancers (TNBCs) are breast cancers that are negative for estrogen receptor (ER), progesterone receptor (PR), and human epidermal growth factor receptor 2 (HER2)." (PMID 30875792, 2019). "In addition, we constructed an ingredients-targets-diseases network that show that RYNXC treated breast cancer by regulating the ESR1, PGR, and PTGS2." (PMID 30906412, 2019). "The prognosis of patients with multifocal breast cancer was either not affected by estrogen and/or progesterone receptor expression or even involved a worse etiopathology for the vitamin D receptor-positive patients." (PMID 31731733, 2019). "TNBC accounts for 10–20% of diagnosed breast cancers and is characterized by the negative expression of progesterone receptor (PR), estrogen receptor (ER), and human epidermal growth factor receptor 2 (HER2)." (PMID 31584090, 2019). "Weight increase in breast cancer patients after diagnosis could be due to age, menopause status, ER/PGR (oestrogen receptor/progesterone receptor) status, hormone replacement therapy, and other factors." (PMID 30883598, 2019). "Taken together, these results provide further evidence that some ER−/PgR+ cases do not reflect a technical artifact, but are a distinct group of breast carcinomas." (PMID 30066060, 2019). "The existence of progesterone receptor (PgR) expression in oestrogen receptor (ER)-negative breast carcinoma is controversial." (PMID 30066060, 2019).
breast cancer (continued). "In pet rabbits, 63% of mammary carcinomas lacked expression of ER-α and progesterone receptor, but 93% contained variable numbers of calponin-positive tumor cells." (PMID 31569405, 2019). "Triple-negative breast cancer (TNBC) is an aggressive subset of breast carcinomas that lack expression of estrogen receptor (ER), progesterone receptor (PR), and human epidermal growth factor receptor-2 (HER2)." (PMID 30791936, 2019). "All breast cancers tested were hormone-receptor-positive (oestrogen receptor average 11.1 ± 2, progesterone receptor average 9.8 ± 3.8) and Her2/neu negative (score 0: 34%, score 1+: 64%, and score 2+ with negative FISH analysis: 2%)." (PMID 30112216, 2018). "Human breast cancer is a heterogenous disease, which can be classified into different groups depending on the presence or absence of estrogen receptor (ER), progesterone receptor (PR), and human epidermal growth factor receptor 2 (HER2) expression." (PMID 30134816, 2018). "Breast cancer patients with positive expression of estrogen receptor (ER) or progesterone receptor (PgR) without expression of HER2 receptor are good candidates for endocrine therapy with fewer toxicities but equivalent treatment outcomes to chemotherapy." (PMID 29581979, 2018). "High expression of VEGF-C was also favorably associated with survival in patients with luminal B, HER-enriched and TNBC breast cancer subtypes and ER/PgR-negative and HER2-negative tumors." (PMID 30063723, 2018). "The study comprised 802 women (median age 40 years, range 19–76) with oestrogen receptor, progesterone receptor, and human epidermal growth factor receptor type 2 negative breast cancers, who had no relatives with breast or ovarian cancer." (PMID 29514593, 2018). "According to the statuses of the estrogen receptor (ER), progesterone receptor (PR), and human epidermal growth factor receptor-2 (HER-2), breast cancer can be classified into four distinct molecular subtypes, including luminal-type, basal type, HER-2 positive, and normal." (PMID 30202238, 2018). "In addition, four cytokeratin genes (KRT8, KRT16, KRT17, and KRT19) and eight tumor-associated genes (TERT, MUC16/M17S2/CA125, CD44, TWIST1, TACSTD1/EpCAM/CD326/ESA/HEA125/GA733, DPP4/CD26, ESR1, and PGR), were upregulated in CRC and breast cancer samples." (PMID 29882767, 2018). "Here, we analyze 1246 invasive breast cancer samples from the Cancer Genome Atlas and show that human breast cancers that have been subtyped based on their HER2, ESR1, or PGR expression contain four clusters of genes that are differentially expressed across all subtypes." (PMID 30279965, 2018). "Whereas, MDA-MB-231 is a triple-negative/basal-like breast cancer cell line, which is hormone-receptor negative (estrogen-receptor and progesterone-receptor negative) and HER2 negative." (PMID 29895744, 2018). "The term TNBC came into vogue shortly after the introduction of routine HER-2 testing for breast cancer to describe the clinical subset of breast cancer patients whose tumors tested negative for estrogen receptor, progesterone receptor and HER-2 expression." (PMID 29487338, 2018). "Of the three breast cancer cases, two were estrogen receptor (ER)-positive, but were progesterone receptor-negative." (PMID 30237864, 2018). "Any type of breast cancer not expressing genes of the estrogen receptor (ER), progesterone receptor (PR), or human epidermal growth factor receptor 2 (HER2) is referred to as triple-negative breast cancer (TNBC)." (PMID 29547591, 2018). "This is particularly evident for late-stage breast cancer, of which 15% are classified as triple negative breast cancer (TNBC), defined as tumours that lack oestrogen receptor (ER), progesterone receptor (PR), and human epidermal growth factor receptor 2 (HER2) expression." (PMID 30142961, 2018).
breast cancer (continued). "Triple negative breast cancer (TNBC) subtype is a breast cancer subset without ER (estrogen receptor), PR (progesterone receptor) and HER2 (human epidermal growth factor receptor 2) expression, limiting treatment options and presenting a poorer survival rate." (PMID 29393914, 2018). "The aim of this study was to explore the characteristics and prognostic information of estrogen receptor-positive/progesterone receptor-negative (ER+/PR−) male breast cancer." (PMID 30558615, 2018). "High expression of Her2neu gene, in the absence of estrogen receptor (ER) and progesterone receptor (PR) related genes are categorized as Her2neu intrinsic breast cancer subtype." (PMID 30103802, 2018). "In line with that, other breast cancer assays, like the GeneXpert Breast Cancer STRAT4 assay from Cepheid, that also measures the expression levels of ERBB2, ESR1, PGR and MKI67, found that macrodissection of whole tissue sections is not required for accurate assessment of these genes by RT-qPCR." (PMID 30342538, 2018). "MCF-7 is a Luminal A breast cancer cells which is hormone-receptor positive (estrogen-receptor and/or progesterone-receptor positive), HER2 negative, and has low levels of the protein Ki-67, which helps control how fast cancer cells grow." (PMID 29895744, 2018). "Triple negative breast cancer (TNBC) is a subtype of breast cancer (BC) and is defined by the lack of expression of three receptors: the estrogen receptor (ER), progesterone receptor (PR), and the human epidermal growth factor receptor 2 (HER2)." (PMID 30338035, 2018). "Interestingly, molecular subtyping of breast cancers in the clinic is routinely based on immunohistochemical analysis of HER2-, ESR1- and PGR-expression from tumor biopsies and is rarely assessed at a transcriptional level." (PMID 30279965, 2018). "In the research setting, MxIF has also been applied to evaluate signaling pathway changes in mouse salivary glands, estrogen receptor (ER), progesterone receptor (PR), human epidermal growth factor receptor 2 (HER2), and Ki67 colocalization in breast cancer, and other single‐cell analyses." (PMID 29498218, 2018). "Triple-negative breast cancer (TNBC) refers to the breast cancer that does not express the genes for estrogen receptor (ER), progesterone receptor (PR), or human epidermal growth factor receptor 2 (Her2/neu)." (PMID 30175120, 2018). "Triple-negative breast cancers (TNBCs) are defined as a group of breast cancer characterized by lacking of estrogen receptor (ER), progesterone receptor (PgR) and human epidermal growth factor receptor 2 (HER2) protein expression." (PMID 30170605, 2018). "Breast cancers with high CD44 and low CD24 have been associated with the triple negative subtype (negative for estrogen receptor (ER), progesterone receptor (PR), and HER2 receptor) and with poorer prognosis." (PMID 29600163, 2018). "Triple-negative breast cancer (TNBC), characterized by tumors lacking ER, PgR, and Her2 expression, represents approximately 15% of all breast cancer cases." (PMID 30473665, 2018). "Since cells of this cancer lack the three common receptors, estrogen receptor (ER), progesterone receptor (PR), and hormone epidermal growth factor receptor 2 (HER-2), there are as yet no specific clinical drugs or targeting therapies for this kind of breast cancer." (PMID 30096175, 2018). "Triple negative breast cancers (TNBCs) represent 15% of all breast cancer (BC) and are defined by the lack of oestrogen receptor (ER), progesterone receptor (PR) and HER2 expression/amplification." (PMID 29880907, 2018). "Most breast cancer subtypes are ER-positive, but approximately 15–20% do not express ER, PgR, or HER2." (PMID 28851309, 2017). "Up to 10–15% of breast cancers do not express either estrogen receptor (ER)/progesterone receptor (PgR) or HER2 and are thus called triple-negative breast cancer (TNBC)." (PMID 28947965, 2017).